REN (renin)
Description:
Renin is a highly specific endopeptidase, whose only known function is to generate angiotensin I from angiotensinogen in the plasma, initiating a cascade of reactions that produce an elevation of blood pressure and increased sodium retention by the kidney.
Synonyms: ADTKD4; HNFJ2; RTD
Tractability: Small molecule: an approved drug acts on it; a structure with a bound ligand is known; a high-quality ligand is known; it has a high-quality binding pocket; it belongs to a druggable protein family. Antibody: UniProt places it where antibodies can reach, with high confidence; its Gene Ontology location is reachable by antibodies, with high confidence; UniProt predicts a signal peptide or a membrane-spanning region. PROTAC: a small molecule that binds it is known.
Target class: Aspartic protease; Aspartic protease A1A subfamily; Protease; Enzyme; Aspartic protease AA clan
Chemical probes: PD084635, SPH-3127 (high quality), U-75875
Safety:
Unwanted effects reported when the protein is acted on. In parentheses: how it was acted on, where the effect was seen, and who reports it.
edema (source: ClinPGx)
Gene: Protein-coding gene on chromosome 1 (204,154,815 to 204,190,324, reverse strand). Ensembl gene ENSG00000143839.
Subcellular location: Secreted; Membrane
Pathways (Reactome):
Metabolism of proteins: Metabolism of Angiotensinogen to Angiotensins
Gene Ontology:
Molecular function: aspartic-type endopeptidase activity; peptidase activity; protein binding; signaling receptor binding; endopeptidase activity; insulin-like growth factor receptor binding
Biological process: angiotensin maturation; kidney development; proteolysis; regulation of MAPK cascade; regulation of blood pressure; cellular response to xenobiotic stimulus; gene expression; juxtaglomerular apparatus development; male gonad development; mesonephros development; response to cAMP; response to cGMP; response to immobilization stress; response to lipopolysaccharide; response to xenobiotic stimulus
Cellular component: apical part of cell; extracellular region; membrane; plasma membrane
Genetic constraint (gnomAD): Loss-of-function variants: 42 observed, 50.83 expected, observed/expected ratio (o/e) 0.83, 90% interval 0.64 to 1.07. The upper end of that interval is the gene's LOEUF score, 1.07, which puts it in group 4 of 6, group 1 being the genes least tolerant of losing a copy. Missense variants: 443 observed, 548.72 expected, observed/expected ratio (o/e) 0.81, 90% interval 0.75 to 0.87. Synonymous variants: 196 observed, 214.48 expected, observed/expected ratio (o/e) 0.91, 90% interval 0.81 to 1.03.
Gene-disease validity (ClinGen):
ClinGen rates the evidence that REN causes each of these diseases.
familial juvenile hyperuricemic nephropathy type 2 (autosomal dominant): Definitive.
renal tubular dysgenesis of genetic origin (autosomal recessive): Definitive. An instance of renal tubular dysgenesis that is caused by a modification of the individual's genome.
Homologues: Orthologues: chimpanzee REN (99% identical), macaque REN (99% identical), pig REN (73% identical), dog REN (72% identical), guinea pig REN (72% identical), mouse Ren1 (70% identical), rat Ren (66% identical), rabbit REN (53% identical), tropical clawed frog ren (50% identical), zebrafish ren (50% identical), Drosophila melanogaster CG17134 (35% identical), Drosophila melanogaster Bace (34% identical), and 12 more. Paralogues in human: NAPSA (40% identical), CTSD (39% identical), CTSE (36% identical), PGA3 (34% identical), PGA4 (34% identical), PGA5 (34% identical), PGC (32% identical), BACE2 (25% identical), BACE1 (25% identical).
Diseases named in the same sentence as REN in open-access papers:
REN is named in the same sentence as 682 diseases in open-access papers, as found by Europe PMC text mining. Sharing a sentence is not in itself a finding about the gene and the disease. The quoted sentences say what the papers report.
Hypertension (2,753 papers, 2002 to 2026). The presence of chronic increased pressure in the systemic arterial system. "Background/Objectives: Blood renin and electrolyte levels are associated with blood pressure and hypertension." (PMID 41598580, 2026). "We identified 36 proteins significantly associated with hypertension and observed a characteristic pattern featuring lower Renin, sRAGE, ghrelin, and IL-1RAcP, and higher TFPI, QORL1, HSP70, and C5a in hypertensive individuals." (PMID 42020520, 2026). "While HCs are generally associated with an increased risk of hypertension, the mechanism is not well understood, and a complex interplay between steroid hormones, the renin-angiotensin system (RAS), and blood pressure is inferred." (PMID 41323407, 2025). "This suggests that vitamin D deficiency affects renin and aldosterone expression in patients with hypertension, confirming the concept that vitamin D deficiency affects RAAS." (PMID 41048520, 2025). "WC, a marker of visceral fat, is a better predictor of hypertension than BMI due to its closer association with insulin resistance, renin-angiotensin-aldosterone system (RAAS) activation, and pro-inflammatory cytokine release." (PMID 40895853, 2025). "This deficiency in mice promotes renal renin expression and the subsequent production of the vasoconstrictor angiotensin II, leading to the development of hypertension." (PMID 41426862, 2025). "It is tightly regulated by the renin–angiotensin–aldosterone system, which is also considered one of the causal relationships between obesity and hypertension." (PMID 40004011, 2025). "The activated renin–angiotensin system and its main mediator, angiotensin II (Ang II), have been implicated in the prothrombotic state associated with hypertension." (PMID 39959581, 2025). "In these patients, hypertension is associated to renin-angiotensin system activation, residual aortic arch abnormalities, and impaired aortic elasticity." (PMID 40260103, 2025). "Previous studies have reported that NO-deficient hypertension is linked to left ventricular hypertrophy because it raises renin and testosterone levels, activates ACE, and increases the expression of ATI, which has a direct vasoconstrictive effect." (PMID 40137963, 2025). "Hypertension is a widely recognized sequala of kidney damage, which is associated frequently with the renin–angiotensin system of blood pressure control." (PMID 40863329, 2025). "miR-122 has been implicated in the regulation of multiple target genes associated with the renin–angiotensin system, thereby influencing key pathological processes such as hypertension and cardiovascular fibrosis." (PMID 40565979, 2025). "Using logistic regression, preoperative renin plasma concentration above the upper normal level (46.1 μUI/mL) was independently associated with the occurrence of hypertension (OR = 2.49, 95% CI = 2.001–5.03, p = 0.001)." (PMID 40283210, 2025). "Historically, renal biopsies for pediatric IgAN were often performed at more advanced stages of disease progression, marked by significant renal function loss, hypertension, or persistent proteinuria despite optimal renin-angiotensin system blockade." (PMID 40939118, 2025). "Recent publications have shown that many risk factors, such as hypertension, renin-angiotensin system activation, and cardiorenal injury were implicated in CVD and CKD including hemodialysis." (PMID 41221515, 2025). "Much rarer causes of renin-driven hypertension include Page kidney resulting from an external kidney compression, which activates RAAS, and reninoma, a benign tumor of juxtaglomerular cells with only ≈100 cases published to date." (PMID 39821533, 2025). "Clinical features associated with LS can be recognised in an early-onset resistant arterial hypertension, associated with hypokalaemia and kaliuresis, metabolic alkalosis, suppressed plasma renin activity and low serum aldosterone levels." (PMID 40540150, 2025).
Hypertension (continued). "CKD caused hypertension by an interplay of factors, including water-sodium retention, renin-angiotensin system overactivation, and endothelial dysfunction, which were common pathological factors of CAVD." (PMID 40356984, 2025). "Renovascular hypertension should be considered in children with suspected secondary hypertension, particularly when associated with elevated plasma renin, hypokalemia, or severe hypertension requiring more than two antihypertensive agents to be controlled." (PMID 40493279, 2025). "AME represents a rare form of pseudo-hyperaldosteronism characterised by very early-onset and severe hypertension, associated with low renin levels and hypoaldosteronism." (PMID 40540150, 2025). "Because of the association of severe hypertension and hypokalemia, the subsequent work-up focused on the causes of renin-mediated hypertension." (PMID 40546339, 2025). "Excessive salt intake and the renin-angiotensin system (RAS) activation are both major causes of hypertension." (PMID 40425782, 2025). "Patients with Val259Met and Tyr348Asn variants present with hypertension after age 50, normal aldosterone-renin ratio values, but ACTH-stimulated aldosterone hypersecretion, in the presence of normal adrenal glands on abdominal imaging." (PMID 40540150, 2025). "The hypertension is usually associated with the hyperactivity of the renin, ACE or angiotensin receptor." (PMID 40430466, 2025). "ACTH also increases the production of other weak mineralocorticoids such as 11-deoxicorticosterone, and it augments the activity of the renin—angiotensin—aldosterone system amongst other mechanisms which can further cause hypertension and hypokalemia." (PMID 40636382, 2025). "This mutation appears to be an activating MR mutation that results in hypertension accompanied by low levels of renin and aldosterone." (PMID 40441250, 2025). "Renin-angiotensin-aldosterone system overactivity has been linked to the development of hypertension." (PMID 40370871, 2025). "Renal markers of water homeostasis, renin‐angiotensin‐aldosterone system alteration as well as kidney inflammation have been used to assess renal involvement in hypertension and associated kidney injury." (PMID 41070523, 2025). "Dysregulation of REN expression has been implicated in diverse pathologies, particularly hypertension, renal diseases, and kidney tumors." (PMID 40534868, 2025). "We examine proposed mechanisms underlying the programming of offspring hypertension by sweeteners, encompassing oxidative stress, dysregulated nutrient sensing signals, abnormal renin-angiotensin system, transcriptome changes, and dysbiotic gut microbiota." (PMID 39911806, 2025). "Alarge prospective study from Canada found that a higher aldosterone-to-renin ratio(ARR) was associated with a greater risk of incident hypertension (adjusted OR, 1.29[95% CI, 1.03-1.62]).Similarly, a study by Markou and cols." (PMID 41312955, 2025). "Other possible mechanisms implicated in the sex differences in fetal programming of hypertension are related to the sympathetic nervous system and renin–angiotensin system, being relevant the implication of sex hormones." (PMID 40321100, 2025). "Both serum renin and aldosterone levels were significantly elevated, which at the time was attributed to the typical causes of hypertension." (PMID 40989803, 2025). "The study’s primary objective was to assess the prospective association between vitamin D biomarkers and hypertension risk, alongside their interrelationship with renin production." (PMID 41516172, 2025). "The mechanisms by which obesity causes hypertension include alterations in adipose-derived hormones, insulin resistance, sympathetic nervous system overactivation, stimulation of the renin-angiotensin-aldosterone system, and renal sodium retention." (PMID 39963158, 2025).
Hypertension (continued). "Primary aldosteronism (PA), characterized by dysregulation of aldosterone productiondespite suppression of plasma renin, is recognized as the most common cause ofsecondary hypertension." (PMID 41196931, 2025). "In the KEGG pathway analysis, signaling pathways associated with hypertension, such as Renin secretion, Calcium signaling pathway, Aldosterone synthesis and secretion, and Vascular smooth muscle contraction, were enriched." (PMID 38907084, 2025). "Heavy metal exposure promotes hypertension by impairing NO signaling, inducing oxidative stress, disrupting Ca2+ signaling in vascular smooth muscle, causing renal damage, and altering the renin–angiotensin system." (PMID 41614871, 2025). "Intriguingly, REN transcription has been shown to be regulated by the WT1 gene (specifically the WT1-KTS isoform), which is frequently mutated in WT patients and associated with elevated plasma renin levels and hypertension." (PMID 40534868, 2025). "Mutations or dysregulation of WT1 were further linked to elevated REN expression, hypertension, and exacerbated tumor progression." (PMID 40534868, 2025). "Increased serum aldosterone is directly related to increased BP and new onset hypertension risk, particularly in primary, or renin-independent, aldosteronism, a prevalent cause of uHTN and rHTN." (PMID 40850955, 2025). "At the same time, both estrogens and progestins have been implicated in hypertension, by means of the activation of the renin-angiotensin-aldosterone system (RAAS), altered endothelial function, and oxidative stress." (PMID 40075003, 2025). "Obesity is a significant risk factor for hypertension and can increase blood pressure via several mechanisms, including overactive renin-angiotensin system, increased arterial stiffness, and PVAT dysfunction." (PMID 41227271, 2025). "The accumulation of mineralocorticoid precursors (deoxycorticosterone) causes low-renin hypertension and hypokalemic alkalosis." (PMID 40313596, 2025). "This research examined the differences in renin levels among various subgroups of complications and identified diverse associations with glucose metabolism in individuals with hypertension in comparison to those with normal blood pressure." (PMID 40106408, 2025). "The metabolic disorder of the renin-angiotensin-aldosterone system is usually related to hypertension, which can cause an excessive retention of Ang II in the blood vessels." (PMID 40342326, 2025). "Although sodium chloride is positively associated with hypertension, recent evidence implicates chloride ions as the principal mediator of blood pressure elevation and renin–angiotensin–aldosterone system activation." (PMID 40507150, 2025). "It is typically characterized by hypertension and hyponatremia and can be caused by a number of disorders including kidney failure, malignant hypertension, thiazide use, renin-secreting tumors and renal ischemia." (PMID 40493279, 2025). "This review examines AngII from a different perspective, exploring the link between the renin–angiotensin–aldosterone system and cardiovascular risk beyond hypertension, with particular emphasis on atherosclerosis development and progression." (PMID 40806655, 2025). "In contrast to previous literature reporting activation of RAAS in OSA, causing elevated renin and subsequently aldosterone, our patients with hypertensive OSA demonstrated a lower renin with higher aldosterone compared to the healthy subjects." (PMID 40289102, 2025). "In Africa, gene-based analyses of 78 variants have shown an association of a component of the renin-angiotensin-aldosterone system with essential hypertension." (PMID 40244094, 2025). "Third, inappropriate activation of the renin-angiotensin-aldosterone system by IR contributes to water and sodium retention and high blood pressure, ultimately increasing the risk of cardiovascular and cerebrovascular disease." (PMID 40013162, 2025).
Hypertension (continued). "The excessive activation of the sympathetic nervous system, which is associated with high blood pressure, inhibits miR-181a expression, and thus increases renin activity, leading to increased blood pressure." (PMID 40565979, 2025). "End-organ damage is linked to plasma renin activity, which only manifests after chronic, untreated essential hypertension." (PMID 40342812, 2025). "The pathogenesis of hypertension is associated with alterations in vascular structure and tension, the activation of the sympathetic nervous system, the activation of the renin–angiotensin–aldosterone system, and insulin resistance." (PMID 38255767, 2024). "This mutation, previously identified by Rayner in a South African cohort, is associated with low-renin-low-aldosterone hypertension and pre-eclampsia in black African and mixed-ancestry individuals." (PMID 38541065, 2024). "Previous case reports and studies have reported associations between HCC and hypertension, likely from abnormalities in the renin‐angiotensin system." (PMID 39713744, 2024). "Subclinical forms of PA are probably responsible for a large proportion of patients with the low-renin phenotype associated with elevated blood pressure (BP) or arterial hypertension." (PMID 38586159, 2024). "The stimulation of the pro-inflammatory pathway and the activation of the renin–angiotensin–aldosterone system (RAAS) by increased adiposity cause hypertension and increase IR, which are important risk factors for renal injury." (PMID 39598097, 2024). "Numerous candidate genes have been implicated in the development of hypertension, with genes in the renin-angiotensin aldosterone system (RAAS) being the focal point of investigation." (PMID 39666621, 2024). "Vitamin D receptor (VDR) gene is implicated in hypertension vulnerability due to its role in regulating the renin-angiotensin system (RAS) and blood pressure." (PMID 38483874, 2024). "Recent studies have documented the association of OFR with the increased activity of the renin‐angiotensin‐aldosterone system (RAA) in hypertension." (PMID 38780511, 2024). "Obesity is also linked to the activation of the renin-angiotensin-aldosterone system, resulting in increased renal vascular resistance, salt retention, and hypertension, all of which can contribute to kidney injury." (PMID 39553097, 2024). "By demonstrating how auricular acupuncture affects the renin-angiotensin system, this research will offer significant new information on the mechanism underlying the action of auricular acupuncture in hypertension." (PMID 38300960, 2024). "Overexpression of renin, specifically in the principal cells of the collecting duct, is associated with hypertension in a transgenic mouse model." (PMID 39273497, 2024). "Renal artery stenosis is said to be significant with hemodynamic reperfusions, thus causing an imbalance of the renin-angiotensin-aldosterone cascade, resulting in accelerated hypertension." (PMID 39099900, 2024). "Earlier research in Chinese, Dutch, Arab, and American populations found a link between the REN (10607 G>A) polymorphism and hypertension, in addition to other diseases, such as stroke and left ventricular hypertrophy, although results were contradictory." (PMID 38935682, 2024). "Obesity is associated with hypertension through various mechanisms, including chronic vascular inflammation, oxidative stress, activation of the renin–angiotensin–aldosterone system (RAAS), and sympathetic overdrive." (PMID 38202263, 2024). "This association is predominantly attributed to hypertension-induced activation of the renal renin–angiotensin system (RAS), disruption of the blood–brain barrier, and neuronal damage triggered by endothelin and ischemic events." (PMID 39581996, 2024). "Hypertension is associated with the activation of the renin-angiotensin-aldosterone system, leading to sodium and water retention, which contributes to increased blood volume and blood pressure." (PMID 39114538, 2024).